SMN1-AS1 (SMN1 antisense RNA 1)
Synonyms: SMN-AS1
Gene: Long non-coding RNA gene on chromosome 5 (70,931,244 to 70,932,840, reverse strand). Ensembl gene ENSG00000285204.
Homologues: Paralogues in human: SMN2-AS1 (100% identical).